LINC00158 (long independently transcribed non-coding RNA 158)
Synonyms: C21orf42; NCRNA00158
Gene: Long non-coding RNA gene on chromosome 21 (25,374,242 to 25,431,701, reverse strand). Ensembl gene ENSG00000185433.
Diseases named in the same sentence as LINC00158 in open-access papers:
LINC00158 is named in the same sentence as 5 diseases in open-access papers, as found by Europe PMC text mining. Sharing a sentence is not in itself a finding about the gene and the disease. The quoted sentences say what the papers report.
bladder cancer (1 paper, 2024). "Although information on the functionality of these ncRNAs remains limited, it has been reported that Linc00158 overexpression inhibits apoptosis by promoting autophagy in spinal cord injury and apoptosis associated transcript in bladder cancer (AATBC) stimulates mitochondrial function in adipocytes." (PMID 39605035, 2024).
renal carcinoma (1 paper, 2022). A carcinoma arising from the epithelium of the renal parenchyma or the renal pelvis. "The results showed the relative expression values of LINC01934, LINC00158, and AC007728.2 in renal cancer tissue were substantially greater than in healthy tissue." (PMID 35719925, 2022).
LINC00158 also shares sentences with these, for which no sentence is quoted: asthma (1 paper); infection (1); osteoarthritis (1).